TNF (tumor necrosis factor)
Diseases named in the same sentence as TNF in open-access papers (continued):
Sharing a sentence is not in itself a finding about the gene and the disease.
Sepsis (continued). "The present study showed that treatment with rSj-Cys significantly reduced the level of TNF-α and IL-6 in sera (systematic) and their mRNAs in cardiac homogenate (local), suggesting the regulatory effects of rSj-Cys on local (cardiac) and systematic (sepsis) immune system." (PMID 32423469, 2020). "Furthermore, we observed again that TNF-α is related to the circadian response in sepsis." (PMID 32226779, 2020). "Therefore, we characterized a novel THRIL/miR-19a/TNF-α pathway in sepsis." (PMID 32944003, 2020). "Sepsis and hemorrhagic shock result from accumulation of monocytes and activated neutrophils in various organs where they produce large amounts of cytotoxic cytokines (e.g., TNF and IL-1β), reactive oxygen species, and reactive nitrogen species which cause organ damage and, ultimately, death." (PMID 32027657, 2020). "Therefore, THRIL is upregulated in sepsis and may sponge miR-19a to upregulate TNF-α, thereby promoting lung cell apoptosis." (PMID 32944003, 2020). "During gram‐negative bacteria‐induced sepsis, lipopolysaccharide (LPS) drives the systemic production of inflammatory genes, such as interleukin (IL)‐1, IL‐6, IL‐8 and tumor necrosis factor‐alpha (TNF‐α), which all induce sepsis‐associated pathology." (PMID 30207412, 2019). "However, this upward trend was reversed by MRS/MRM treatment, indicating that methane could reduce the levels of TNF-α and IL-6 to offer a protective effect for tissues and organs during sepsis." (PMID 30779706, 2019). "Therefore, we hypothesized that TNF has a dual role in sepsis, namely a mediating and a protective role, and that protection might be obtained by TNFR1-specific inhibition." (PMID 31787972, 2019). "Additionally, IL-1 and TNF-α are potent inducers of NO inducible synthase gene expression, with a corresponding increase in endothelial production of NO, the primary factor responsible for vascular hypotension that occurs in sepsis." (PMID 30949497, 2019). "It is shown that stimulated kidneys during sepsis could activate the nuclear factor-kappa B (NF-κB) signaling pathway to generate numerous pro-inflammatory cytokines including interleukin (IL)-6 and tumor necrosis factor-α (TNF-α)." (PMID 31084615, 2019). "Lnc‐THRIL relative expression was positively correlated with levels of CRP (r = 0.421, P < 0.001), PCT (r = 0.251, P = 0.008), TNF‐α (r = 0.357, P < 0.001), and IL‐1β (r = 0.305, P = 0.001), but not correlated with IL‐17 level (r = −0.072, P = 0.459) in sepsis patients." (PMID 31257645, 2019). "Indeed, clinical studies showed that subgroups of patients with sepsis might benefit from anti-inflammatory treatment strategies such as IL-1 receptor blockade or anti-TNF treatments." (PMID 31781099, 2019). "There is growing evidence that pro-inflammatory cytokines such as interleukin-1 (IL-1), IL-6, and tumor necrosis factor-alpha (TNF-α) play a central role in the systemic complications of acute pancreatitis and may be involved in diaphragmatic dysfunction during sepsis." (PMID 30466472, 2018). "The inconsistent reports of TNFα and IL-1β concentrations in neonatal sepsis may be a confounded by the kinetics and short half-life of circulating TNFα and IL-1β and the timing of sample collection relative to the onset of sepsis." (PMID 30555806, 2018). "Increased levels of IL-8 and IL-10 were associated with sepsis, whereas TNFα was not changed." (PMID 30555806, 2018). "Among the inflammatory cytokines, tumor necrosis factor-α (TNF-α), interferon-γ (IFN-γ), and interleukin-1β (IL-1β) are detected in the blood of patients with sepsis and induce septic shock-like conditions when administered in animals in vivo, suggesting their critical pathogenic roles in sepsis." (PMID 29928698, 2018). "Additionally, Takinib reduces TNF serum levels following LPS challenge in a murine model of sepsis." (PMID 30451876, 2018).
Sepsis (continued). "Moreover, PTX3 is described as induced by TNFα but TNFα signaling pathway is known to be disrupted in sepsis which suggests that PTX3 may be induced through other signaling pathways especially if PTX3 has a major anti-inflammatory effect in sepsis." (PMID 30687307, 2018). "Moreover, in the sepsis model TNF-α expression is induced in response to S. aureus inoculation." (PMID 30123776, 2018). "Inflammatory cytokines, such as IL-1β, TNF-α, and IFN-γ, are detected in the blood of patients with sepsis and induce septic shock-like conditions when animals are administrated with these inflammatory cytokines, suggesting that these cytokines have key pathogenic roles in sepsis." (PMID 29928698, 2018). "Moreover, at 50 μg/kg, TNF-α levels compare with those induced by low dose LPS (100 μg/kg i.p.)and, at 250 μg/kg, levels compare with those induced in mouse LPS and cecal ligation and puncture models of sepsis." (PMID 27633985, 2017). "Furthermore, we suggest that the balance between TNF and IL-10 may be altered in a favorable way in the initial as well as later stages of sepsis development by the combined treatment." (PMID 28261486, 2017). "Additionally, the increase of interleukin-1 (IL-1), tumor necrosis factor (TNF), and lipopolysaccharide (LPS) during sepsis could also activate SOD." (PMID 29230271, 2017). "Thus, attenuated increase of TNF in the initial phase of sepsis development may be particularly beneficial." (PMID 28261486, 2017). "Another limitation was that the in vivo association of rs11666254 with FPR2/ALX expression and TNF-α level could not be confirmed in this study because of difficulties in obtaining blood samples from some sepsis patients." (PMID 28679406, 2017). "However, serum concentrations of inflammatory cytokine IL-6 and TNF-α during sepsis were similar." (PMID 28976973, 2017). "Moreover, the ADAM17 substrate TNFα occurs at high levels in the blood during sepsis promoting neutrophil rigidity and the upregulation of integrin adhesion molecules, in turn causing occlusion of the microvasculature, ischemia, and tissue destruction through the release of cytotoxic factors." (PMID 28487846, 2017). "This meta-analysis suggests that the -308G/A gene polymorphism in the TNF-α gene may contribute to risk of sepsis and septic shock, but not risk of mortality." (PMID 29212277, 2017). "Nonetheless, our results support the interdependence of ET-1 and TNF-α and the possible impact of these peptides on liver dysfunction in sepsis and the results of the study may contribute to a better understanding of the role of ET-1 in septic liver failure and the potential clinical impact." (PMID 28542386, 2017). "Therefore, TNF-α control is a potential treatment strategy for sepsis and septic shock." (PMID 28912777, 2017). "Another study showed a significantly increased IL‐6 level and a trend toward higher levels of TNF‐α in Treg‐depleted mice during sepsis, which supported the hypothesis that the hyper‐inflammatory response during the early phase of sepsis was intensified in mice lacking Treg cells." (PMID 28621034, 2017). "Sepsis in general can result in multiple organ failure and death as a consequence of uncontrolled activation of the innate immune system with high circulating levels of pro-inflammatory cytokines such as interleukin 6 (IL-6), IL-8, IL-1β and tumor necrosis factor α (TNFα)." (PMID 28428949, 2017). "Additionally, thermo-dysregulation is mediated by TNF-α because knockout TNF receptor of mice could attenuate hypothermia in early sepsis." (PMID 28661460, 2017). "The pro-inflammatory cytokines selectively measured in our patients (TNF, IL-8, and IL-6) represent some of the key pro-inflammatory mediators involved in what has been referred to as the “cytokine storm”, responsible for the clinical features that characterize sepsis." (PMID 31058274, 2017).
Sepsis (continued). "The elevatedexpression of TNF-α, IL-1β, and IL-6 is an important step in the pathogenesis of ALI andacute respiratory distress syndrome.Moreover, in the case of humans with ALI or sepsis, a persistent elevation of thesecytokines was associated with a poor prognosis." (PMID 26648090, 2016). "Similarly, the amounts of TNF in supernatants from CB-stimulated PBMCs were significantly (p = 0.04 and p = 0.05, respectively) lower in the patients with severe sepsis (59 pg/ml) than in the healthy controls (311 pg/ml) and the patients with cured Q fever (480 pg/ml)." (PMID 27441846, 2016). "Quite surprisingly, mTPOR-MBP was not able to inhibit the increase in plasma concentrations of TNF-α, IL-6 and IL-10 observed in both models, a well-known phenomenon that participates in the initiation and progression of organ damage during systemic inflammation and sepsis." (PMID 26963510, 2016). "In addition to inflammatory cytokines, other factors have recently been shown to mediate the lethal late phase of sepsis; these factors include tumor necrosis factor (TNF)-α, IL-1, high-mobility group box-1 (HMGB1) protein, and nuclear architectural chromatin-binding protein." (PMID 27011792, 2016). "This study is part of a larger study to evaluate the characteristics of sepsis patients and its purpose is to study the relationship between gender and mortality due to sepsis and to identify differences if any between the cytokine levels specifically IL-6, IL-10 and TNF alpha between the genders." (PMID 26649014, 2015). "Although the signaling pathways through which sepsis confers myocardial protective effects have as yet to be elucidated, an important role has been proposed for the MAPK JNK, with additional reports of increased TNF-α-induced apoptosis associated with JNK inhibition." (PMID 26215802, 2015). "In addition, the levels of TNF-α and IL-6 have been shown to reach a peak as early as 3 h after the onset of sepsis, and the degree of increase may reflect the severity of sepsis." (PMID 25780398, 2015). "Therefore, we wanted to investigate that therapeutic strategies may reduce the severity of sepsis by decreasing proinflammatory cytokines like TNF-alpha." (PMID 25948886, 2015). "Moreover, the rs653765 CC genotype in severe sepsis showed a higher ADAM10 level compared to healthy groups, and the rs653765 CC polymorphism had a strong impact on the production of the ADAM10 substrates CX3CL1, IL-6R and TNF-α." (PMID 25888255, 2015). "Therefore, miR-23b may play a significant role in the pathogenesis and progression of sepsis by inhibiting the expression of inflammatory factors, including NF-κB, TNF-α, IL-6, ICAM-1, E-selectin and VCAM-1." (PMID 25780398, 2015). "In addition, HIF-1α could significantly upregulate TNF-α to progress inflammatory response in the sepsis process formation and alveolar macrophages activated by lipopolysaccharide (LPS)." (PMID 26715469, 2015). "Here, a negative correlation was observed between p70S6K activation and TNF-α levels in hippocampus, indicating the negative impact of LPS-induced sepsis in this kinase linked to diverse cellular processes, including protein synthesis, mRNA processing, glucose homeostasis, cell growth and survival." (PMID 25169902, 2014). "Similarly to TNF, MK2-deficient mice were also sensitized to CLP-induced sepsis." (PMID 25185746, 2014). "However, TNF-α is an early marker of inflammation commonly used in sepsis models." (PMID 24826081, 2014). "If confirmed, this may support the implementation of repeated massage interventions over 24 hours in the PICU to stimulate HF + LF power and help coping with acute stress, similar to data in mice with sepsis where vagus nerve stimulation reduced the secretion of TNF-alpha and improved the outcomes." (PMID 25587344, 2014). "Therefore, insights into the regulatory mechanisms of cardiomyocyte TNF-α expression may provide a therapeutic modality for cardiac dysfunction during sepsis." (PMID 24304472, 2014).
Sepsis (continued). "Recently, RIPK3-dependent necrosis has been shown to be responsible for the mortality of septic mice induced either by TNF-α injection or polymicrobial sepsis, suggesting that targeting necrotic cells could be a novel and promising therapeutic approach for improving sepsis outcome." (PMID 24996547, 2014). "In animal models of sepsis, the role of TNF may vary depending upon the type of infection." (PMID 24886820, 2014). "C-reactive protein (CRP), tumor necrosis factor-α (TNF-α) and interleukins are among the first-discovered potential biomarkers for sepsis, among which IL-6 and IL-10 may be good choices as biomarkers while CRP and TNF-α are nonspecific biomarkers for inflammation." (PMID 24977412, 2014). "The increased bacterial clearance that was observed in this study might initially suggest a better outcome against sepsis in these animals; however, the increased inflammation, as was observed with the increased TNF-α levels, may also be detrimental to sepsis outcomes." (PMID 24826081, 2014). "Thus, TNF-α as a reliable biomarker for sepsis is compromised." (PMID 25614712, 2014). "To prove this hypothesis, neonatal cardiomyocytes from C57BL/6 mice were used and we found that propofol could decrease the generation of TNF-α in cardiomyocytes and alleviate cardiac failure through its inhibitory effect on the production of O2− during sepsis." (PMID 25180066, 2014). "Neutralization of TNF-α could alleviate the development of sepsis in animal model." (PMID 23431240, 2013). "Since IL-8 and TNF-α were demonstrated to be necessary to initiate an effective inflammatory process and could be evaluated as good parameters to predict the outcome of sepsis, plasma levels of these two proinflammatory cytokines of rats were thus measured in the present study." (PMID 24369483, 2013). "The pathogenesis of sepsis is attributable, at least in part, to dysregulated systemic inflammatory responses characterized by the excessive accumulation of various proinflammatory mediators, such as tumor necrosis factor (TNF) or interleukin (IL)-1, interferon-gamma (IFN-γ), and nitric oxide (NO)." (PMID 24098466, 2013). "Therefore, agents attenuating TNF-α and/or IL-1β expression may have potential as treatments for prevention of lethal sepsis." (PMID 24260470, 2013). "This local regulation of cytokines in the wound might be influenced by the systemic elevation of pro-inflammatory cytokines like tumor necrosis factor-alpha (TNF-α) during sepsis leading to a disruption of the inflammatory reaction in the beginning of the wound healing process." (PMID 24086305, 2013). "To underline that TNF-α secretion was not an epiphenomenon with regard to monocyte apoptosis, we also investigated the reaction in response to the pro-inflammatory cytokine IL-6, the secretion of which is well documented in clinical sepsis." (PMID 23349721, 2013). "Apoptosis can be induced via both the extrinsic (TNF-α, Fas ligand) and intrinsic pathways (mitochondrial) during sepsis, and prevention of lymphoid cell apoptosis could markedly attenuate parameters of sepsis and improve survival." (PMID 23233853, 2012). "Further, we investigated the correlation between rs1800629 genotypes and TNF-α concentrations in peripheral blood mononuclear cells (PBMCs) of healthy volunteers exposed to lipopolysaccharides (LPS) ex vivo, and the association between rs1800629 and TNF-α serum levels in severe sepsis patients." (PMID 23029405, 2012). "This idea is also supported by an ex vivo study by others demonstrating that continuous exposure of IL-1 or TNF-α provides a signal to downregulate leptin in human adipose tissue, though acute inflammation such as sepsis may rather upregulate circulating leptin levels transiently." (PMID 22685600, 2012).
Sepsis (continued). "Considering the important role of TNF-α, LT-α, TNFR1 and TNFR2 in the pathogenesis of severe sepsis, we hypothesized that genetic variation in TNF, LTA, TNFRSF1A and TNFRSF1B might be associated with susceptibility to and outcomes from severe sepsis in Chinese Han population." (PMID 23029405, 2012). "However, C5a exposure alone could not stimulate normal thymocyte apoptosis, suggesting that other factors such as TNF-α and Fas ligand-induced by sepsis were indispensible for C5-indued apoptotic death of thymocytes." (PMID 23233853, 2012). "Indeed, the pioneering experiments of Carswell and Old that identified TNF used whole bacteria as stimuli in macrophage sepsis simulation settings, and we have previously demonstrated that macrophage responses to live, antibiotic-treated staphylococci serve as a powerful model system." (PMID 21266054, 2011). "Thus, TNFα blockers could increase the severity of the sepsis, but further controlled studies are needed to assess this hypothesis." (PMID 20637100, 2010). "Leptin concentrations are increased during infection and sepsis, in accordance with the observation that leptin expression is up-regulated by various pro-inflammatory cytokines, including tumor necrosis factor-α (TNF-α), interleukin-1 (IL-1) and leukaemia inhibitory factor." (PMID 21040518, 2010). "TNF-α is also known to downregulate PPARγ function by several mechanisms (see Ye 2008 for a recent review), and LPS treatment was shown to downregulate PPARγ expression in Kupffer cells both in vitro and in an animal model of sepsis through a TNFα -dependent mechanism." (PMID 19756185, 2009). "By using the CLP model of sepsis in the rat, we have shown that organ dysfunction occurred early after sepsis and that the liver residential macrophages, Kupffer cells, play an important role in producing proinflammatory cytokines (for example, tumor necrosis factor-alpha [TNF-α]) in sepsis." (PMID 18680601, 2008). "Furthermore u-PA is potently upregulated by the proinflammatory cytokines TNF-α and IL-6 in a variety of human cancer cell lines in vitro and the u-PA system is significantly activated by infection and sepsis in vivo as evidenced by increased circulating levels of u-PA." (PMID 17242699, 2007). "Our negative findings may be due to the fact that our population differs from the previous reported studies showing a positive correlation, e.g. studies of meningococcal disease alone (PAI-1, TLR4 and TNF-α) and of patients with severe sepsis in intensive care settings (TNF-α and TLR4)." (PMID 17877801, 2007). "Hence, TNF-α is a valuable indicator of sepsis induction in experimental settings." (PMID 16893450, 2006). "For example, within a few years it began to dominate the sepsis literature, and the virulence of different strains of influenza, a disease that is a standard clinical misdiagnosis for imported malaria, has now been expressed in terms of their capacity to induce TNF." (PMID 17029647, 2006). "• The three polymorphisms evaluated in the present study (the TNF-α-308 promoter polymorphism, the polymorphism in the first intron of the TNF-β gene, and the IL-10-1082 promoter polymorphism) appear not to influence outcome in patients admitted to the hospital with sepsis." (PMID 16859504, 2006). "In addition, inhibiting TNF successfully treated the metabolic acidosis of sepsis in a double blind trial in premature infants, and immunizing mice against GPI, a malarial toxin selected for its capacity to induce TNF production, inhibited metabolic acidosis in a mouse malaria model." (PMID 17029647, 2006). "Single-cell RNA sequencing of a sepsis-induced ALI mouse model and in vitro assays revealed marked upregulation of NEDD4L in endothelial cells under ALI-related pathological stimuli (LPS, TNFα, H2O2)." (PMID 41943017, 2026). "This study aimed to analyze the effects of glutamine and arginine combination (GAC) on TNF-α, NF-κB, IL-8, and MMP-8 expressions in sepsis." (PMID 42294010, 2026).